CCDC6 (coiled-coil domain containing 6)
Diseases named in the same sentence as CCDC6 in open-access papers (continued):
Sharing a sentence is not in itself a finding about the gene and the disease.
tumor (continued). "It has been recently postulated that the CCDC6 impairment derived from its truncation in fusion oncogenes, enhances tumour progression and impacts on selective response to therapeutics offering new chances for a tailored therapy and novel challenges to overcome drug resistance." (PMID 29455670, 2018). "Interestingly, in HCT116 FBXW7−/− the stabilized CCDC6 protein appeared mainly localized in the cytosol, a condition that has been related to tumor growth." (PMID 25885523, 2015). "The genome locus for CCDC6 is commonly rearranged in various tumours." (PMID 23145146, 2012). "These considerations make CCDC6 an attractive candidate that could help pre-cancers overcome a Dna Damage Response (DDR)-dependent barrier against tumour progression." (PMID 22655027, 2012). "After the progression, the molecular testing revealed CCDC6-RET fusion in a liver metastasis, two novel RET fusions (IL6ST-RET and SLC41A3-RET), and an ALK fusion with a mutation allele frequency of 0.19% in circulating tumor DNA (ctDNA), including the known EGFR 19del." (PMID 41907614, 2026). "Furthermore, this regulatory effect may be dose‐dependent, indicating a potential threshold for CCDC6‐mediated tumour progression." (PMID 41035371, 2025). "Besides, CCDC6 was found to be involved in regulating the EMT process in tumours." (PMID 41035371, 2025). "In our study, tumor tissues from 83 PTC patients were investigated to determine the prevalence of CCDC6::RET and NCOA4::RET rearrangements in Thailand and to explore the association between the mRNA expression of CCDC6::RET and NCOA4::RET rearrangements and clinicopathology." (PMID 37188126, 2023). "Additionally, using WGCNA and machine learning, three diagnostic gene signatures (CAST, CCDC6, and ERLIN1) for the high level mitophagy subtype were obtained, which were closely associated with tumour immune microenvironment and chemotherapy sensitivity in PAAD." (PMID 35938160, 2022). "However, the deubiquitinase USP7 has many substrates including several tumor suppressors and CCDC6, the tumor suppressor whose reduced levels impair HR DNA repair and sensitize cancer cells to treatment with PARP inhibitors, as reported in several malignancies." (PMID 31242618, 2019). "In addition to the hypothetical role of CCDC6 on the TK stability and on the development of “on-target” resistance, the impairment of CCDC6 in tumours carrying the fusions may induce “off targets” effects as well as “off targets” resistance." (PMID 29455670, 2018). "Thus, CCDC6 would work as tumor suppressor in inhibiting the CREB1-dependent gene expression." (PMID 25970781, 2015). "Interestingly, the vast majority of PTC bearing RET/PTC1 failed to express wild type CCDC6 from the non-rearranged allele, suggesting a potential tumor suppressor function of this gene." (PMID 22363533, 2012). "The loss of checkpoint and of repair accuracy, which we observe when CCDC6 is deleted or silenced, might favour genome instability and might represent an early independent event of a multistep carcinogenetic process in primary tumours." (PMID 22655027, 2012). "Multidimensional in vivo and in vitro assays demonstrated that modulation of CCDC6 expression significantly influenced tumour cell proliferation, invasion and EMT, thereby driving tumour progression." (PMID 41035371, 2025). "To investigate the role of CCDC6 in tumour development, we screened two iCCA cell lines, RBE and HuCCT1, which exhibited the most significant differences in CCDC6 expression among three iCCA cell lines, as determined by qPCR." (PMID 41035371, 2025). "Six rare fusion partners were also identified: GOPC, MPRIP, NUP210L, ZCCHC8, CCDC6, and CFAP53, each present in one tumor." (PMID 38835380, 2024). "The majority of rearrangements were KIAA1549-BRAF rearrangements (n = 47; 85%), with only one tumor each harboring BCAS1, CCDC6, GIT2, or PTPRZ11 as a fusion partner." (PMID 36854806, 2023).
tumor (continued). "The univariate Cox regression analysis revealed that CCDC6 expression, AJCC clinical stage, tumor volume, invasion of local organs or lymph nodes and clinical state are associated with the OS of patients with HCC." (PMID 36186907, 2022). "Some recurrent fusions appear to be almost exclusively clonal (CCDC6-RET, BRAF-KIAA1549, and TMPRSS2-ERG), suggesting that gain-of-function SVs occur early during tumor development." (PMID 33831375, 2021). "In summary, our molecular data together with a confirmed tumor response to the selective RET inhibitor LOXO-292, suggest that this patient's ATC was driven by the identified CCDC6-RET gene fusion." (PMID 32292131, 2020). "The identification of CCDC6 fusions to other partners (LIP I, CTNNA3, and KITLG) in this type of tumor have been also reported." (PMID 31877762, 2019). "The CCDC6 and USP7 expression was evaluated semi-quantitively on 46 bladder cancer tumor samples; each tumor sample was present in duplicate in our TMA and analysed blindly by two pathologists (left)." (PMID 30786932, 2019). "Ponatinib displayed 79% tumor growth inhibition in the NCOA4-RET model (CR1520) and near complete regression in the CCDC6-RET model (CR2518)." (PMID 30038711, 2018). "In our study, qRT-PCR analysis showed SHC4 (15.85-fold), SOS2 (2.78-fold), CCDC6 (6.18-fold), and KRAS (5.92-fold) were up-regulated significantly in tumor tissues." (PMID 23285163, 2012). "Although functional assays have demonstrated the tumour‐promoting role of CCDC6, its mRNA expression did not exhibit significant prognostic value in survival analysis of public cohorts (OPE001105 database, N = 244, p = 0.19; TCGA database, N = 30, p = 0.20)." (PMID 41035371, 2025). "In addition, CCDC6 has subsequently been described as being involved in other rearrangements, in addition to RET, in different neoplasias." (PMID 39684377, 2024). "IHC results also indicate that the tumor tissues expressed significantly higher CCDC6 protein than the matched adjacent non-carcinoma tissues." (PMID 36186907, 2022). "Liquid biopsy is useful in detecting tumor heterogeneity, particularly when diverse resistance mechanisms develop in different tumor sites, as reported in the case of an NSCLC with an EGFR exon 19del and T790M, which had a liver progression with an acquired CCDC6-RET fusion." (PMID 35454838, 2022). "Moreover, PAAD tumours were insensitive to Erlotinib, Sunitinib and Imatinib in the high mitophagy subtype and high CAST, CCDC6, and ERLIN1 expressed subtypes." (PMID 35938160, 2022). "Then, we believe that CCDC6 could represent a useful predictive and reliable biomarker for the use of PARP inhibitors in tumour testis." (PMID 34841108, 2021). "In particular, “off targets” effects of TKIs could be considered a better therapeutic option in thyroid or lung tumours that carry CCDC6/RET fusion protein, in order to avoid tumour progression and TKIs resistance." (PMID 29455670, 2018). "CCDC6 impairment upon fusions, altering the DDR process in TK addicted cells, might promote the tumour heterogeneity by enhancing ongoing error-prone DNA replication with differential selection pressures and drug sensitivity." (PMID 29455670, 2018). "Recently, low levels of CCDC6 protein, in NSCLC, have been correlated with tumor prognosis." (PMID 25885523, 2015). "Furthermore, the mRNA expression of CAST, CCDC6 and ERLIN1 could potentially predict the tumour’s sensitivity to Erlotinib, Sunitinib and Imatinib." (PMID 35938160, 2022). "If this molecular mechanism will prove to be crucial for cancer cell proliferation, the absence of CCDC6 may have important therapeutic effects for the targeting of the EGFR family members in determined tumours." (PMID 29455670, 2018). "Other than the CCDC6-RET fusion, which is expected to generate an oncogenic driver, it is difficult in most cases to predict the function of a given mutation (i.e. gain in oncogenic activity or a loss of tumor suppressor activity, or neither)." (PMID 23405175, 2013).
tumor (continued). "Thus, CCDC6, when fused to ROS1 and RET kinase, could be imagined as a predictive biomarker of resistance to conventional single mode therapy and provides indications about the tumour sensitivity to PARPi in combination with TKI in NSCLC." (PMID 29455670, 2018). "In addition, if CCDC6 is mutated or downregulated, the lack of genomic stability might indirectly enhance KRAS-driven oncogenesis by promoting a permissive environment for tumor growth." (PMID 39684377, 2024). "In order to test the significance of combined tissue IHC-expression of CCDC6 and USP7 we performed a non-parametric Spearman correlation test that proved to be extremely significant across all the tumor samples." (PMID 30786932, 2019). "Among all the clinical variables, age, gender, tumor diameter, differentiation grade, invasion of local organs or lymph nodes, AJCC clinical stage, tumor location, and death were not significantly correlated with CCDC6 expression." (PMID 36186907, 2022).
cancer (47 papers, 2012 to 2026). A tumor composed of atypical neoplastic, often pleomorphic cells that invade other tissues. "This dominant-negative behavior has been previously observed with truncated and mutated CCDC6 isoforms in other cancer cell models." (PMID 41417832, 2026). "Mutations and gene rearrangements in CCDC6 have been observed in different cancer types, leading to resistance against radiation and chemotherapy." (PMID 40141028, 2025). "In conclusion, the loss of CCDC6 or the overexpression of CCDC6 point mutant protected the testicular murine and human cancer cells from reactive oxygen species by limiting the regulated cell death by apoptosis and ferroptosis." (PMID 34841108, 2021). "In effect, loss of CCDC6 has also been implicated as a biomarker to sensitizing cancer cells to treatment with PARP inhibitors." (PMID 32580154, 2020). "Here, we observed that fusion with CCDC6 was associated with strong overexpression of ANK3 in all three cancers." (PMID 33097743, 2020). "Our data suggest, that loss of CCDC6 function can create a prosperous environment for the formation of cancer." (PMID 22363533, 2012). "To study the functional consequences of loss of CCDC6 we applied a highly efficient lentiviral shRNA knock down strategy in several human cancer cell lines." (PMID 22363533, 2012). "Here we report that following genotoxic stress, loss or inactivation of CCDC6 in cancers that carry the CCDC6 fusion, accelerates the dephosphorylation of pH2AX S139, resulting in defective G2 arrest and premature mitotic entry." (PMID 22655027, 2012). "Given that CCDC6 has been implicated in DNA damage repair and the regulation of epithelial‐mesenchymal transition in other cancers, we hypothesise that CCDC6 may not only function as an oncogene fusion partner in iCCA but also act as an independent oncogene." (PMID 41035371, 2025). "Conversely, in cancers which carry CCDC6 mutated forms, or that have lost CCDC6 expression, cancer cells may lose their abilities to repress xCT/SLC7A11 and to promote ferroptosis." (PMID 34841108, 2021). "Furthermore, mutations in the cancer driver gene, CCDC6 (93%), suggest potential benefit from PARP inhibitor treatment." (PMID 34245124, 2021). "Moreover, loss or inactivation of CCDC6 in cancers, by accelerating the dephosphorylation of the histone γH2AX results in defective G2 arrest and premature mitotic entry." (PMID 29455670, 2018). "RET gene fusions have been reported as driver genes for various types of cancer, including thyroid, lung, intestine, pancreas, and breast, and fusions such as CCDC6-RET, NCOA4-RET, and KIF5B-RET are known to be frequently seen." (PMID 40647546, 2025). "According to COSMIC, 25% of recurring fusions are RTK oncofusions such as EML4::ALK and CCDC6::RET which have been extensively studied as drivers of many different cancer types." (PMID 38833619, 2025). "Known to be a cancer driver gene, CCDC6 (coiled-coil domain containing protein 6) is expressed as a 55 KDa nuclear and cytosolic protein involved in apoptosis as well as the DNA damage response." (PMID 36186907, 2022). "We applied the TIMER2 approach to analyze the expression profiles of CCDC6 across various cancer types in the TCGA database." (PMID 36186907, 2022). "According to preclinical research, attenuation of CCDC6 in several cancer cell cultures enhances sensitivity to PARPi, which have the ability to work in concert with cisplatin." (PMID 35964058, 2022). "To investigate why CCDC6-RET protein granule formation is kinase-independent, we swapped the fusion partners EML4 and CCDC6 to generate two additional oncogenic RTK fusion oncoproteins that are also present in human cancers, EML4-RET and CCDC6-ALK." (PMID 33848463, 2021). "Among the affected genes, ETV1, CCDC6, and NCOA4 are causally implicated in cancer according to the Cancer Gene Census." (PMID 32580154, 2020).
cancer (continued). "As the NHEJ process is prone to errors, the cancer cells defective for CCDC6 show tolerance to the DNA damage induced by several mutagens, including cis-platinum." (PMID 31877762, 2019). "In vitro evidence indicates that the silencing of CCDC6 in cancer cells releases the PP4c phosphatase-activity, lowers the levels of phospho H2AXS139 and reduces the number of DNA repairing foci upon exposure to DNA damage inducers." (PMID 31877762, 2019). "The silencing of CCDC6 in cancer cells exposed to DNA damage also decreases the levels of the G2-checkpoint phospho-protein Chk1 and shortens the G2 phase, allowing a premature entrance into the mitosis." (PMID 31877762, 2019). "In several in vitro cancer cell systems CCDC6 protein levels have been correlated with cancer cell tolerance to DNA damage, resistance to cisplatinum and sensitivity to poly (ADP-ribose) polymerase inhibitors (PARPi)." (PMID 31877762, 2019). "Reduced levels of the tumor suppressor protein CCDC6 sensitize cancer cells to the treatment with PARP-inhibitors." (PMID 28415632, 2017). "We wonder if the use of specific USP7 inhibitors would enhance CCDC6 turnover in order to sensitize cancer cells to the PARP inhibitors in combination with standard chemotherapies." (PMID 25885523, 2015). "Further specification of the exact pathways in which CCDC6 is implicated and identification of its interacting partners will be necessary to unravel the molecular mechanisms of cancers, harboring CCDC6 alterations." (PMID 22363533, 2012). "The loss or dysfunction of CCDC6 could exacerbate the oncogenic effects of KRAS, as impaired DDR would allow for the unchecked accumulation of mutations, fueling cancer progression." (PMID 39684377, 2024). "The number of CCDC6 molecular alterations identified has grown in human cancers." (PMID 36186907, 2022). "Interestingly, the in vitro conditional expression of CCDC6 dominant negative mutants protected cancer cells from oxidative stress, also impairing the stress-induced cell death." (PMID 34841108, 2021). "Additionally, the in vitro conditional expression of CCDC6 truncated mutants, which act as dominant negative of the endogenous wild type protein, determines tolerance to oxidative damage in cancer cells, impairing the stress-induced cell death." (PMID 34841108, 2021). "Since the HR defect is accompanied by sensitivity to PARP inhibitors, we aimed to characterise and quantify the outcomes of CCDC6 downregulation on olaparib sensitivity in cancer testicular cells by measuring cellular metabolic activity as an indicator of cell viability." (PMID 34841108, 2021). "Furthermore, we observed that CCDC6 is normally highly expressed in ovarian, endometrial and breast compared to the other cancer types, as well as in normal ovary and uterine tissues." (PMID 33097743, 2020). "Novel recurrent cases were also found in ovarian (n = 6), endometrial (n = 2) and breast (n = 2) cancers involving CCDC6, a coiled-coil domain protein, fusing with ANK3 at the 3′ end, which encodes the ankyrin G protein that plays a key role in cell proliferation, as result of tandem duplications." (PMID 33097743, 2020). "Our findings suggest that the NSCLC patients carrying the CCDC6 fusions, beside the kinase inhibitors, might also benefit of the inclusion of PARPi in order to prevent cancer cell resistance." (PMID 31877762, 2019). "The targeting of USP7 to reduce CCDC6 levels appears to be useful for the establishment of new therapeutic approaches in cancer treatment, since it could also affect the stability and turnover of the TKs fused to CCDC6." (PMID 29455670, 2018). "Preclinical studies indicate that the attenuation of CCDC6 in cancer confers resistance to cisplatinum and sensitizes the cancer cells to the small molecule inhibitors of Poly (ADP-ribose) polymerase (PARP1/2) in accordance with its role in the DNA damage response." (PMID 29455670, 2018).